ENSG00000252192
Gene: Small nucleolar RNA gene on chromosome 12 (122,492,113 to 122,492,241, reverse strand). Ensembl gene ENSG00000252192.
Homologues: Orthologues: mouse Gm54495 (47% identical). Paralogues in human: SNORA9 (71% identical), SNORA9B (67% identical).